STIM1 (stromal interaction molecule 1)
Diseases named in the same sentence as STIM1 in open-access papers (continued):
Sharing a sentence is not in itself a finding about the gene and the disease.
T-cell immunodeficiency (3 papers, 2016 to 2021). A broad classification of disorders that affect the cell-mediated aspect of the immune response. "One of these children, who died from severe disseminated KS at the age of two, harboured a homozygous splice‐site stromal interaction molecule 1 (STIM1) mutation resulting in T cell immunodeficiency." (PMID 33043529, 2021). "Rare homozygous deletion mutations in Stim1 in humans create an immune phenotype including both T lymphocyte immunodeficiency and antibody-mediated autoimmune disease." (PMID 32300198, 2020). "They revealed a homozygous splice-site mutation in the stromal interaction molecule 1 (STIM1) gene that is very important for immunity, and they identified STIM1 deficiency and the associated primary T-cell immunodeficiency as the genetic cause of severe KS in childhood." (PMID 27043613, 2016).
thyroid tumor (3 papers, 2021 to 2023). A benign or malignant neoplasm affecting the thyroid gland. "In xenograft zebrafish model, the STIM1 knockdown decreased human thyroid tumor growth and also activated apoptosis." (PMID 38089882, 2023). "Surprisingly, an increased STIM1 gene expression but not ORAI1 was observed in the tumor adjacent normal tissue, compared to the normal thyroid tissue, indicating a possible role of STIM1 in the initiation of thyroid tumor formation." (PMID 34155535, 2021). "Interestingly, we observed that STIM1 was significantly upregulated not only in thyroid tumor tissues (TP) but also in the tumor adjacent thyroid tissues (NT), compared to the normal thyroid tissues (GTEX)." (PMID 34155535, 2021). "Furthermore, a comparison of STIM1 expression in normal thyroid solid tissues (GTEX dataset), thyroid tumor tissues (TP) and tumor adjacent normal thyroid tissues (NT) was determined." (PMID 34155535, 2021).
triple-negative breast carcinoma (3 papers, 2018 to 2022). An invasive breast carcinoma which is negative for expression of estrogen receptor (ER), progesterone receptor (PR), and human epidermal growth factor receptor 2 (HER2). "Phemindole-induced triple negative breast cancer cell death was reverted by restoration of STIM1 expression, which strongly supports a role for SOCE in triple negative cell survival." (PMID 30558192, 2018). "More recently, Chakraborty and coworkers have reported that phemindole, a synthetic di-indole derivative with anti-carcinogenic activity in triple negative breast cancer cells, reduces SOCE by down-regulation of STIM1 expression." (PMID 30558192, 2018). "In the present study we have investigated the role of STIM1 and Orai1 N-linked glycosylation in SOCE in non-tumoral breast epithelial cells as well as in ER+ and triple negative breast cancer (TNBC) cells." (PMID 36612199, 2022). "Here we show that while STIM1 and Orai1 N-linked glycosylation has a significant effect on SOCE in non-tumoral breast epithelial cells, both ER+ and triple negative breast cancer (TNBC) cells are unaffected by this mechanism." (PMID 36612199, 2022).
uterine carcinoma (3 papers, 2020 to 2024). A carcinoma involving a uterus. "As the target gene of miR-185, matrix-interacting molecule 1 (STIM1) can affect the release of the placenta by regulating the concentration of Ca2+ in uterine cancer epithelial (UCE) cells." (PMID 39272385, 2024).
Acanthocytosis (2 papers, 2017 to 2024). "Previous research from our group has demonstrated that lithium significantly enhances ORAI1 and STIM1 transcript and protein levels, along with increasing SOCE in the neurodegenerative disease Chorea-Acanthocytosis." (PMID 38903530, 2024). "The present study uncovers a novel pathophysiological mechanism in chorea-acanthocytosis, i.e. deranged regulation of ORAI1 and STIM1 expression with subsequent impairment of store operated Ca2+ entry (SOCE)." (PMID 28743945, 2017).
Anhidrotic ectodermal dysplasia (2 papers, 2020 to 2025). "Patients also had non‐immunological symptoms including congenital muscular hypotonia and anhidrotic ectodermal dysplasia, which are typical of CRAC channelopathy due to LOF mutations in STIM1 and ORAI1." (PMID 32609955, 2020).
Arrhythmia (2 papers, 2017 to 2019). Any cardiac rhythm other than the normal sinus rhythm. "Furthermore, redistribution of STIM1 and ORAI1 from interior regions to the IDs resulted in augmented SOCE in myocytes from arrhythmia-prone (CPVT) hearts." (PMID 31308393, 2019).
Arterial thrombosis (2 papers, 2022 to 2023). The formation of a blood clot inside an artery. "STIM1-deficient chimeric mice display a regular tail bleeding time but present a decreased thrombus formation and a prolonged time to vessel occlusion in a mechanically- and chemically-induced in vivo mouse model of arterial thrombosis." (PMID 35203269, 2022). "Since STIM1/Orai1-mediated SOCE in platelets is sufficient for thrombus formation without affecting hemostasis, it is a promising target for the treatment of thrombo-occlusive disorders including arterial thrombosis, myocardial infarction and ischemic stroke." (PMID 35203269, 2022).
atrial fibrillation (2 papers, 2019 to 2022). A disorder characterized by an electrocardiographic finding of a supraventricular arrhythmia characterized by the replacement of consistent P waves by rapid oscillations or fibrillatory waves that vary in size, shape and timing and are accompanied by an irregular ventricular response. "It is possible that STIM1–SOCE regulation changes during the progression of early atrial myopathy, even turning into a transition after the stage of persistent atrial fibrillation." (PMID 31226824, 2019).
Chronic lymphocyte leukemia (2 papers, 2019 to 2022). "Chronic lymphocyte leukemia (CLL) is associated with dysregulated Ca2+ signaling in dependence with not only STIM1 and Orai1, but also TRPC1." (PMID 36612099, 2022).
colon adenocarcinoma (2 papers, 2015 to 2018). "To evaluate the association between HSP27 and STIM1 expressions, we performed HSP27 and STIM1 immunostaining on the other tissue microarray of colon adenocarcinoma." (PMID 30544747, 2018).
colorectal adenocarcinoma (2 papers, 2022 to 2024). The most common type of colorectal carcinoma. "Among them, the expression of Orai proteins, as well as STIM1 and TRPC1 is enhanced at the transcript and protein level in the colorectal adenocarcinoma cell line HT‐29." (PMID 38514909, 2024). "Our results indicate that treatment of the colorectal adenocarcinoma cell lines HT‐29 and Caco‐2 with inanimate Lacticaseibacillus paracasei and Lactiplantibacillus plantarum results in a significant attenuation of SOCE due to downregulation of Orai1 and STIM1 expression." (PMID 38514909, 2024).
dermatitis (2 papers, 2020 to 2024). An inflammatory process affecting the skin. "Mice deficient in both Stim1 and Stim2 in T cells develop a lymphoproliferative disorder and dermatitis, characterized by eosinophilia and augmented IgE and IgG1 responses." (PMID 38578569, 2024). "For example, urolithin A, an ellagitannin metabolite, dose-dependently inhibited (10-50 μM) proliferation and activation of CD4+, by calcium influx impairment through the STIM1/STIM2–Orai1–SOCE pathway, but its effect on dermatitis is still unknown." (PMID 32575730, 2020).
endothelial dysfunction (2 papers, 2022 to 2025). In vascular diseases, endothelial dysfunction is a systemic pathological state of the endothelium (the inner lining of blood vessels) and can be broadly defined as an imbalance between vasodilating and vasoconstricting substances produced by (or acting on) the endothelium. "For example, Orai1 and STIM1 mediate histamine-induced endothelial inflammation, and Orai1 is involved in endoplasmic reticulum stress–induced endothelial dysfunction." (PMID 35369318, 2022).
eosinophilia (2 papers, 2019 to 2024). "Abolished GATA3, IRF4, and BATF expression in Stim1/2-deficient Tregs may thus explain the type 2 autoimmunity in Stim1/2Foxp3 mice, which is characterized by elevated Th2 cytokines, increased IgE levels and eosinophilia." (PMID 30862784, 2019).
esophageal cancer (2 papers, 2014 to 2022). A primary or metastatic malignant neoplasm involving the esophagus. "Among factors that promote cell migration, the expression level of small GTPases Ras or Rac is critical in STIM1- and/or Orai1-dependent cancer types, as reported in breast and esophageal cancer cells." (PMID 36612099, 2022).
familial Alzheimer disease (2 papers, 2018 to 2020). A degenerative disease of the brain that causes gradual loss of memory, judgment, and the ability to function socially. "In both sporadic and familial Alzheimer’s disease, a decrease of STIM1 protein levels accounts for the alteration of Ca2+ handling that compromises neuronal cell viability." (PMID 32916960, 2020).
follicular thyroid cancer (2 papers, 2021 to 2022). "Based on these results, we then investigated the importance of the STIM1 and ORAI1 channels in follicular thyroid cancer ML-1 cells, a cell line showing the highest expression of STIM1 and ORAI1 compared to normal human thyroid cells." (PMID 34155535, 2021). "In another comparison, we found the STIM1 expression was significantly higher in follicular thyroid cancer tissues compared to the papillary thyroid cancer tissues." (PMID 34155535, 2021). "The knockdown of the calcium signalling proteins TRPC1, STIM1 and ORAI, increased the expression of TRβ1, but decreased that of Runx2 in human follicular thyroid cancer ML-1 cells." (PMID 36497320, 2022). "However, we found STIM1 borderline upregulated (p = 0.058) but not ORAI1 in follicular thyroid cancer tissues." (PMID 34155535, 2021).
fungal infection (2 papers, 2020). "Mutations of STIM1 and ORAI1 were also reported to affect patients with viral, bacterial, and fungal infections via abolishing the SOC influx and immune system." (PMID 33182378, 2020). "Together, these data demonstrate that STIM1 in T cells is critical for immunity to systemic fungal infection." (PMID 32609955, 2020). "Taken together, we here show that STIM1 is a critical regulator of antifungal immunity by regulating the expression of cytokines and metabolic pathways in non‐pathogenic Th17 cells, which may explain the increased susceptibility of patients with STIM1 and ORAI1 mutations to fungal infections." (PMID 32609955, 2020).
head and neck cancer (2 papers, 2020 to 2025). A primary or metastatic malignant neoplasm affecting the head and neck. "In this study, GPP130 expression was found to be elevated in head and neck cancer cells and was proposed as a downstream target of STIM1." (PMID 40649939, 2025). "As shown for head and neck cancer, it is plausible that the knockdown of GPP130 also leads to the perturbation of Stromal Interaction Molecule 1 (STIM1)-GOLIM4 signal axis in A549 cells, thereby reducing the cellular growth." (PMID 40649939, 2025).
hypertensive nephropathy (2 papers, 2020 to 2025). Kidney damage that results from chronically elevated blood pressure; complications include glomerular damage resulting in proteinuria and hematuria. "Recently, STIM1 mutation was reported to influence T cell functions, which may increase the risk of hypertensive renal disease." (PMID 33348924, 2020).
injury (2 papers, 2020 to 2022). Damage inflicted on the body as the direct or indirect result of an external force, with or without disruption of structural continuity. "A previous study has reported that STIM1 expression is significantly increased at both mRNA and protein levels following traumatic brain injury, and downregulation of STIM1 leads to increased preservation of neuronal viability and inhibition of apoptosis." (PMID 33328896, 2020).
Insulin resistance (2 papers, 2017 to 2023). Increased resistance towards insulin, that is, diminished effectiveness of insulin in reducing blood glucose levels. "Hepatocytes lacking STIM1 displayed stress, increased glucose production and insulin resistance, whereas over-expression of STIM1 in the liver of obese mice significantly improved glucose intolerance." (PMID 29243589, 2017). "In addition, exercise can improve insulin resistance; however, STIM1 ablation in cardiomyocytes reduced exercise-induced AKT phosphorylation at Ser473." (PMID 37685995, 2023).
lupus (2 papers, 2022 to 2024). "Similarly, in systemic lupus erythematosus (SLE) hyperactivation of cGAS-STING signaling in T cells also required suppression of Ca2+ homeostasis, but whether STIM1 was involved is not clear." (PMID 36139387, 2022).
Lymphadenopathy (2 papers, 2017 to 2019). Enlargement (swelling) of a lymph node. "Splenic CD4+ T cells of Stim1/2Foxp3 mice also showed higher Ki-67 expression compared to WT control mice suggesting that enhanced T cell proliferation contributes to the splenomegaly and lymphadenopathy of Stim1/2Foxp3 mice." (PMID 30862784, 2019).
metabolic syndrome (2 papers, 2019). A cluster of metabolic risk factors for CARDIOVASCULAR DISEASES and TYPE 2 DIABETES MELLITUS. "Nonetheless, aldosterone promotes an MR-specific increase in TRPC1/5 and STIM1 protein expression in ARVMs, as seen in metabolic syndrome adrenal chromaffin cells, in coronary arteries, and in NRVMs." (PMID 31878108, 2019).
metastatic cancer (2 papers, 2023 to 2024). A carcinoma which has spread from the original site of growth to another anatomic site. "In addition, the expression of STIM1 in primary and metastatic cancer is a matter of controversy in different cancers." (PMID 38532463, 2024). "In addition, the blockage of STIM1-mediated Ca2+ signaling enhances cell adhesion by inhibiting the turnover of focal adhesions, which hampers the rapid migration of cells, including metastatic cancer cells." (PMID 36677874, 2023). "However, the expression STIM1 in metastatic cancer is a matter of controversy." (PMID 38532463, 2024).
metastatic melanoma (2 papers, 2014 to 2024). A melanoma that has spread from its primary site to another anatomic site. "We found that both STIM1- and Orai1-knockdown inhibited cell migration in metastatic melanoma cell lines." (PMID 24586666, 2014). "STIM1 was overexpressed in metastatic melanoma and lung cell lines compared to primary cell line." (PMID 38532463, 2024). "We found that proliferation was reduced in STIM1-knockdown metastatic melanoma cell lines." (PMID 24586666, 2014).
Myalgia (2 papers, 2016 to 2021). "STIM1-R304Q (a constitutively active form of STIM1) has been found in human patients with skeletal muscle phenotypes such as muscle weakness, myalgia, muscle stiffness, and contracture." (PMID 34439731, 2021). "One patient with STIM1 His109Asn had not shown muscle weakness, but myalgia, fatigability, or episodic diplopia." (PMID 27879676, 2016). "An affected individual with STIM1 Phe108Leu had shown myalgia without muscle-related symptoms, including weakness or elevated serum CK." (PMID 27879676, 2016).
myocardial ischemia (2 papers, 2017 to 2022). A disorder of cardiac function caused by insufficient blood flow to the muscle tissue of the heart. "Stromal interaction molecule 1 and inositol 1,4,5-triphosphate receptor (STIM/1IP3R) play an important role in myocardial ischemia–reperfusion injury." (PMID 35841499, 2022).
Parkinson disease (2 papers, 2020 to 2022). A progressive degenerative disorder of the central nervous system characterized by loss of dopamine producing neurons in the substantia nigra and the presence of Lewy bodies in the substantia nigra and locus coeruleus. "Further, application of the neurotoxin that mimics Parkinson’s disease, 1-methyl-4-phenyl-1,2,3,6-tetrahyrdro-pyridine (MPTP), led to increased activity of Cav1.3, and decreased expression of TRPC1 and inhibited thapsigargin mediated STIM1-Cav1.3 interactions." (PMID 35821821, 2022).
peritonitis (2 papers, 2015 to 2024). Inflammation of the peritoneum (tissue that lines the abdominal wall and covers most of the organs in the abdomen). "Importantly, by monitoring the recruitment of adoptively transferred monocytes in an in vivo model of peritonitis, we show that increased infiltration of male monocytes during infection is dependent on STIM1." (PMID 38815866, 2024).
renal carcinoma (2 papers, 2021). A carcinoma arising from the epithelium of the renal parenchyma or the renal pelvis. "Accumulating evidence demonstrates that the upregulation of Orai1/STIM1-mediated SOCE is associated with tumor progression and poor prognosis in multiple cancers including breast, lung, and renal cancer." (PMID 33386992, 2021). "Evidence have shown that STIM1 and ORAI1 regulate proliferation in different cancers, including brain, ovarian, pancreatic, nasopharyngeal, and renal cancers." (PMID 34155535, 2021).
sarcopenia (2 papers, 2024 to 2025). Progressive decline in muscle mass due to aging which results in decreased functional capacity of muscles. "This is of particular medical importance for carriers of STIM1 loss‐of‐function mutations, who may bear a higher risk of developing sarcopenia and a decline in muscle force in later years." (PMID 41354418, 2025).
type 1 diabetes (2 papers, 2018 to 2021). "Here, we show that SOCE-related stromal interaction molecule 1 (STIM1) and Orai1 participate in inappropriate cellular Ca2+ homeostasis, augmenting agonist-induced small intestinal smooth muscle contraction and small bowel transit speed in a mouse model of type 1 diabetes." (PMID 34744757, 2021). "Our results show that in pregnancy and type 1 diabetes ORAI1-3 are up-regulated whereas STIM1 and 2 are down-regulated in pregnancy but only STIM2 in type 1 diabetes." (PMID 30543678, 2018).
type 2 diabetes (2 papers, 2023 to 2025). "In this context, it is interesting to note that SERCA 3 has previously been observed to physically interact with Stim1 to increase Ca2+ stores, and that this interaction was abrogated in platelets isolated from patients with type 2 diabetes." (PMID 40723860, 2025). "Islets from type 2 diabetics were shown to have reductions in STIM1, and deletion of STIM1 from INS-1 pancreatic β-cells was shown to impair SOCE." (PMID 37141277, 2023).
abdominal aorta coarctation (1 paper, 2022). "For example, choline can regulate the expression of key calcium-handling proteins, such as STIM1 and Orai1 and attenuate the angiotensin II-induced elevation of intracellular calcium, thereby alleviating the cardiac remodeling induced by abdominal aorta coarctation in rats." (PMID 36082183, 2022).
acute lymphoblastic leukemia (1 paper, 2022). Leukemia with an acute onset, characterized by the presence of lymphoblasts in the bone marrow and the peripheral blood. "In acute lymphoblastic leukemia (ALL) cells, STIM1‐dependent Ca2+ entry has been linked to PKCβ2 activation and in vascular smooth muscle cells (VSMCs) STIM1 has been linked to increased PLCβ1 activity and subsequent phosphorylation of PKC." (PMID 35179826, 2022).
advanced heart failure (1 paper, 2017). Patients with advanced heart failure have severe limitations, experiences symptoms even while at rest and are mostly bedbound patients. "Although ORAI1 and STIM1 have been described in fibroblasts and human cardiac fibroblasts, their role in fibrosis in patients with advanced heart failure has not been described." (PMID 28126709, 2017).
alopecia (1 paper, 2019). Hair loss usually from the scalp. "Despite normal numbers and activation of tTreg cells in the absence of SOCE, male Stim1/2Foxp3 mice developed a severe disease phenotype with a hunched posture, scaly skin, and alopecia starting around 4 weeks of age." (PMID 30862784, 2019).
amnesia (1 paper, 2022). Pathologic partial or complete loss of the ability to recall past experiences ( AMNESIA, RETROGRADE) or to form new memories ( AMNESIA, ANTEROGRADE). "LPS-induced oxidative stress-activated stromal interaction molecule 1, which is a component of the SOCE machinery in B leukocytes, and scopolamine reportedly contributed to oxidative stress-mediated neurodegeneration in mice with amnesia." (PMID 36558972, 2022).